EPHX1 (epoxide hydrolase 1)
Diseases named in the same sentence as EPHX1 in open-access papers (continued):
Sharing a sentence is not in itself a finding about the gene and the disease.
cancer (continued). "Variations in the expression and activity level of EPHX1 as a result of such polymorphisms could cause individual variations of detoxifying capability, then further influence the risk of chemical carcinogen-induced cancers." (PMID 25261893, 2014). "Moreover, cigarette-smoking status may influence the association of EPHX1 enzyme activity and the related cancer risk." (PMID 21445251, 2011). "Hence, the EPHX1 variants, individually or collectively with other metabolic enzymes, may lead to cancer susceptibility." (PMID 21445251, 2011). "Thus, cigarette-smoking status may influence the association of EPHX1 enzyme activity and the related cancer risk." (PMID 21445251, 2011). "The present cancer meta-analysis was motivated by the idea that performing both single-SNP analysis and two-SNP analysis may provide insights into the relationship between EPHX1 enzyme activity and cancer risk." (PMID 21445251, 2011). "Accumulating evidence implicates EH family members, particularly Ephx1 (microsomal EH) and Ephx2 (soluble EH), in cardiovascular diseases, cancer, neurodegeneration, metabolic disorders, and other pathological conditions." (PMID 42117830, 2026). "Pan-cancer analysis revealed significantly elevated EPHX1 expression in tumor tissues compared to normal counterparts." (PMID 40745342, 2025). "In summary, we demonstrated for the first time that EPHX1 rs1051740 heterozygous genotype is significantly associated with increased risk of AKD in co-dominant and over-dominant model among Thai cancer patients who received cisplatin." (PMID 40526606, 2025). "The connection between EPHX1 and cancer development was further analyzed by correlating EPHX1 expression in tumor tissues with disease progression and clinical outcomes." (PMID 33374956, 2020). "Given the significance of EPHX1 in eliminating carcinogenicity of toxic compounds like epoxides, it could be proposed that these two functional polymorphisms may lead to individual variations of xenobiotic detoxification and further influence susceptibility to chemical carcinogen-induced cancers." (PMID 25261893, 2014). "In the analysis of putative EPHX1 enzyme activity and risk of lung and UADT cancers, obvious between-study heterogeneity was identified for high vs. intermediate (I2 = 53.5%, P = 0.005)." (PMID 21445251, 2011). "Several studies have shown that low expression of EPHX1 is closely associated with different human cancers, including HCC, and that increased expression of EPHX1 suppresses cell proliferation, migration, and cycle progression, as well as inducing apoptosis in HCC." (PMID 36980210, 2023). "Together, these findings indicate that variations in the hydrolysis activity of EPHX1 might influence cancer development." (PMID 33374956, 2020). "The results revealed that neither EPHX1 Tyr113His polymorphism, nor His139Arg polymorphism have significant association with the cancer susceptibility for all comparing models when all studies were accumulated together." (PMID 25261893, 2014). "In order to evaluate the association of these two functional polymorphisms and their enzyme activity with carcinogenesis risk, we analyzed the association of EPHX1 enzyme activity predicted by genotype combination of polymorphism Y113H and H139R with risk of lung and UADT cancers." (PMID 21445251, 2011). "Pooled analysis of lung and UADT cancers revealed that low EPHX1 enzyme activity, predicted by the combination of Y113H and H139R showed decreased risk of these cancers (OR = 0.83, 95%CI = 0.75–0.93) whereas high EPHX1 activity increased risk of the cancers (OR = 1.20, 95%CI = 0.98–1.46)." (PMID 21445251, 2011). "Moreover, EPHX1 might also be involved in chemoresistance to cancers, such as acute myeloid leukemia, by metabolizing antitumor drugs." (PMID 33374956, 2020).
cancer (continued). "In an overall comparison to the putative intermediate EPHX1 activity, low EPHX1 activity decreased risk of lung and UADT cancers significantly (OR = 0.83; 95%CI = 0.75–0.93, P = 0.001) and high EPHX1 activity increased the cancer risk (OR = 1.20; 95%CI = 0.98–1.46; P = 0.081)." (PMID 21445251, 2011). "Among them, EPHX1 and EPHX2 stand out as the most significant members, with their altered expressions reported in several human cancers." (PMID 40507905, 2025). "However, it has not been well clarified whether EPHX1 enzymatic activity is associated with cancer risk." (PMID 21445251, 2011). "To further clarify whether EPHX1 can counteract the pro‐cancer effects of TRIM21, we co‐expressed HIS‐EPHX1 and FLAG‐TRIM21 in BXPC3 and SW1990 cell lines." (PMID 39739616, 2025). "In conclusion, our investigations suggested that the EPHX1 His139Arg polymorphism might not contribute to the susceptibility of all cancer types for overall population, whereas Tyr113His polymorphism might be associated with increased risk of cancer in the Asian and mixed population." (PMID 25261893, 2014). "Putative low EPHX1 enzyme activity may have a potential protective effect on tobacco-related carcinogenesis of lung and UADT cancers, whereas putative high EPHX1 activity may have a harmful effect." (PMID 21445251, 2011). "Thus, putative high EPHX1 enzyme activity was supposed to increase risk lung and UADT cancers rather than decrease the risk as results from overall large sample subgroup analysis suggested." (PMID 21445251, 2011).
tumor (19 papers, 2012 to 2025). "We found that EPHX1 protein levels were significantly higher in HCC tissues compared to adjacent non-tumor tissues." (PMID 40745342, 2025). "Further immunohistochemical (IHC) analysis of paraffin-embedded HCC tissues confirmed cytoplasmic localization of EPHX1 with stronger immunoreactivity in tumor tissues." (PMID 40745342, 2025). "In summary, TRIM21 promotes tumour growth and gemcitabine resistance in PC by inhibiting EPHX1‐mediated arachidonic acid metabolism." (PMID 39739616, 2025). "In a xenograft model using Huh7 cells with stable EPHX1 knockdown, both EPHX1 depletion and regorafenib monotherapy inhibited tumor growth, with maximal suppression achieved by combination therapy." (PMID 40745342, 2025). "Tumor weight analysis corroborated the synergistic effect of EPHX1 knockdown and regorafenib treatment." (PMID 40745342, 2025). "Specifically, in HCC samples, both mRNA and protein levels of EPHX1 were markedly higher than in adjacent non-tumor tissues." (PMID 40745342, 2025). "TRIM21 plays a pivotal role in tumor growth and chemoresistance by regulating EPHX1‐mediated arachidonic acid metabolism." (PMID 39739616, 2025). "This interaction enhanced tumour development by upregulating epoxide hydrolase 1 (EPHX1), thereby promoting proliferation, migration, and metastasis in HCC." (PMID 41379397, 2025). "In a xenograft mouse model of HCC, overexpression of EPHX1 decreased tumor growth, while LINC00205 silencing promoted tumor growth, confirming the in vitro data." (PMID 37111734, 2023). "EPHX1 expression was found to be high in 89% of tumor tissues in primary operable breast cancer, and was associated with poor disease outcome, notably in patients receiving tamoxifen treatment." (PMID 33374956, 2020). "In conclusion, EPHX1 inhibits the anti-tumor effect of regorafenib by activating the JAK/STAT pathway, and the JAK/STAT inhibitor HY-N-1447 can reverse the resistance induced by EPHX1, suggesting that EPHX1 targeting JAK/STAT is an important mechanism of regorafenib resistance in HCC." (PMID 40745342, 2025). "Additionally, we established xenograft tumor models to explore the impact of EPHX1 on the in vivo efficacy of regorafenib." (PMID 40745342, 2025). "Importantly, while the expression of EPHX1 was reduced in HCC tissues compared to adjacent non-tumor tissue, the opposite was observed for miR-184." (PMID 37111734, 2023). "Notably, LDHA, SHC1, and EPHX1 exhibited heightened expression levels in tumor tissues, while MYO6 and TLE1 displayed diminished expression compared to normal tissues." (PMID 37965333, 2023). "Furthermore, EPHX1 was differentially expressed in hepatocarcinoma and liver metastases, when compared to normal liver tissue, suggesting potential implications in tumor progression." (PMID 33374956, 2020). "Collectively, these results demonstrate that EPHX1 is aberrantly overexpressed in HCC, suggesting its potential role in tumor progression." (PMID 40745342, 2025). "Functionally, EPHX1-derived AA promotes ferroptosis and suppresses tumor proliferation, whereas TRIM21-mediated EPHX1 degradation sustains AA depletion, thereby enhancing pancreatic cancer growth and conferring gemcitabine resistance." (PMID 40735642, 2025). "We assessed the protein expression levels of EPHX1 in human HCC tissues and adjacent non-tumor tissues." (PMID 40745342, 2025). "Subsequently, we analyzed DEGs between tumor and normal tissues and selected the top five DEGs with the highest expression, which were SPP1, AKR1C2, AKR1B10, AGT, and EPHX1 in tumor tissues and NKG7, KLRD1, KLRB1, CCL5, and CST7 in normal tissues." (PMID 35967424, 2022).
infection (3 papers, 2013 to 2020). The state of being infected such as from the introduction of a foreign agent such as serum, vaccine, antigenic substance or organism. "Down-regulation of Ephx1 and Pon1 may ensure a certain amount of hydrogen peroxide, a potent antimicrobial agent, is present during pathogen infection; 4) Apoptosis-regulating proteins were significantly modulated." (PMID 23826353, 2013).
genetic disorder (1 paper, 2020). "Mutations of EPHX1 may alter its enzymatic function and lead to Familiar Hypercholanemia, a genetic disorder characterized by high serum bile acid concentrations, itching, and fat malabsorption." (PMID 32033399, 2020).
EPHX1 also shares sentences with these, for which no sentence is quoted: adenocarcinoma (2 papers); leukemia (2); liver disease (2); multiple myeloma (2); type 2 diabetes mellitus (2); acute lymphoblastic leukaemia (1); arthrogryposis (1); cardiovascular diseases (1); cerebrovascular diseases (1); cervical cancer (1); Charcot-Marie-Tooth disease (1); colon cancer (1); colorectal adenoma (1); congenital heart disease (1); deafness (1); diabetic nephropathy (1); Fraser syndrome (1); gastric cancer (1); glioma (1); heart diseases (1); hyperandrogenism (1); Hypercholesterolemia (1); hypospadias (1); Infertility (1); Insulin resistance (1); Kaposi's sarcoma (1); liver cancer (1); liver cirrhosis (1); liver dysfunction (1); lung squamous cell carcinoma (1).
A further 15 diseases each share a sentence with EPHX1 in 1 paper.